C3 (complement C3)
Diseases named in the same sentence as C3 in open-access papers (continued):
Sharing a sentence is not in itself a finding about the gene and the disease.
Alzheimer disease (continued). "Importantly, scRNA-seq analysis identified one inflammatory astrocyte subpopulation (characterized by the upregulation of C3) enriched in TGF-β signaling in Alzheimer’s disease brains." (PMID 35625943, 2022). "Another study examined the cerebrospinal fluid (CSF) samples taken from patients with Parkinson’s disease, Alzheimer’s disease, and multiple system atrophy and found that complement 3 (C3) and CFH were both increased, though to varying ratios depending upon the disease." (PMID 32157596, 2020). "However, the function of the C3 is complex and a protective effect of C3 has been described in experimental models of Alzheimer’s disease, probably as a consequence of favoring the clearance of Aβ plaque." (PMID 27769255, 2016). "Additionally, increased expression of C1, C3 and C4 mRNA has been found in the brains of Alzheimer patients, and is thought to contribute to the progression of Alzheimer’s disease by inducing microglia activation and proinflammatory cytokine release." (PMID 21857943, 2011). "Complement C3 is also known to be a key inflammatory protein activated in Alzheimer disease." (PMID 21139973, 2010). "In addition, studies have demonstrated that the classical pathway complement proteins, C1q, C3, C4 in particular, are involved in the pathology of neurological diseases, including Alzheimer’s disease, through the facilitation Aβ clearance or synapse engulfment by reactive microglia." (PMID 35370615, 2022). "Furthermore, C3 serves as a stage-biomarker of Alzheimer’s disease in CSF." (PMID 28122624, 2017). "Deletion or blockage of C1q, C3, or CR3 in mouse models of Alzheimer’s disease has been shown to protect synapses and prevent cognitive impairments, highlighting the therapeutic potential of complement inhibition strategies." (PMID 41465272, 2025). "Since overactivation of the complement system and C3‐mediated brain injury are common in animals and humans, our findings could lead to the use of a potentially universal strategy for treating several neurological disorders, including Alzheimer's disease (AD), TBI, epilepsy and depression." (PMID 38532579, 2024). "The interaction between complement C3 and APOE-ε4 leads to increased Alzheimer’s disease-related pathology." (PMID 38238858, 2024). "Novel methods were developed and optimised to quantify C1q, C3 fragments and MAC in total and regional brain homogenates and synaptoneurosomes from WT and AppNL−G−F Alzheimer’s disease model mouse brains at 3, 6, 9 and 12 months of age." (PMID 35794654, 2022). "Similar A1 responses are observed in various neurodegenerative conditions, including Alzheimer’s disease (AD), Huntington’s disease (HD), Parkinson’s disease (PD), amyotrophic lateral sclerosis (ALS), and MS, all of which demonstrate positive immunoreactivity for C3 and other A1-specific markers." (PMID 40854886, 2025). "Similarly, the RNA-seq of astrocytes found in brains affected by Alzheimer’s disease (AD) and normal aging reveals microglial-derived IL-1α, C1q and TNF-α induced C3 upregulation in astrocytes, which is regarded as the biomarker of neurotoxic reactive astrocytes." (PMID 35204837, 2022). "Very recent investigations in mouse models of tauopathies and Alzheimer’s disease suggested regulation of the complement 3 receptor (C3aR), that is abundant on astrocytes and microglia, rather than C3 itself as a feasible target for therapies aiming to reduce gliosis and formation of A1-astrocytes." (PMID 31118110, 2019).
breast cancer (61 papers, 2003 to 2026). A primary or metastatic malignant neoplasm involving the breast. "In ClinVar, the CFTR gene is related to cystic fibrosis, the BRCA2 gene is associated with breast cancer and breast-ovarian cancer syndrome, and the C3 gene is associated with complement component 3 deficiency." (PMID 39796280, 2025). "The results in complement-deficient mice were unexpected, as we have previously demonstrated that C1qA and C3 deficiencies are associated with increased Her2 expression and aggressiveness of autochthonous mammary cancers in neuT mice." (PMID 35203439, 2022). "To differentiate between cancer and cisplatin-induced effects, we used a transgenic mouse model of breast cancer expressing a large T-antigen on a C3 promoter (C3TAg) that exhibits the evolutionary spectrum of human breast cancer." (PMID 40298791, 2025). "Vitamin D-binding protein-derived macrophage-activating factor induces apoptosis and phagocytosis in breast cancer cells, whereas C3 is the foremost player in innate immune response manipulated in conventional chemotherapy." (PMID 37900279, 2023). "For instance, CAFs are a major source for complement proteins in melanoma (C1s, C1r, C3, C4a, FB, and C1inh) and breast cancer (C3 and C3a)." (PMID 38003705, 2023). "The mRNA expression showed that all five genes were differentially expressed in breast cancer: C3, GFPT, and GMFG were significantly down-regulated, while CD27 and HLA-DPB1 were significantly up-regulated." (PMID 37287069, 2023). "Of note, complement component 3 (C3), the key molecule in the complement pathway, was significantly upregulated, and the expression of C3 was negatively correlated with that of CAS in breast cancer." (PMID 35403306, 2022). "To validate the relevance of our findings to human disease, we analyzed the expression of C3 in a cohort of breast cancer patients with lung metastasis." (PMID 36184683, 2022). "Together, these results suggest that C3 is critically required for the promotion of lung metastasis of breast cancer cells by LMSCs." (PMID 34707103, 2021). "C3 plays a critical role in the complement system contributing to innate immunity, which again highlights the importance of immunity in breast cancer prediction." (PMID 33435254, 2021). "BMP4 and C3 were significantly expressed in normal tissue as compared to cancerous breast cancer tissues whereas CXCL13 and DKK1 is observed to be expressed in breast cancer tissue as compared to normal breast tissue." (PMID 34754042, 2021). "Common plasma proteins including APOE, ITIH4 and C3 showed significantly different intensity between breast cancer versus ovarian cancer and normal plasma." (PMID 31889940, 2019). "For example, in a mouse model of breast cancer with spontaneous metastatic spread mimicking human malignancy, increased concentrations of C3 were found in plasma and bronchoalveolar lavage indicating increased production of complement proteins." (PMID 30061895, 2018). "In this study, we focused on MSigDB c3 regulator target gene list refinement and their implications for improving downstream analyses in breast cancer." (PMID 28103241, 2017). "The COOH terminal peptide of Pro-collagen type I (PICP, also called C3) is chemotactic for endothelial melanoma and breast cancer cells." (PMID 19226458, 2009). "In many tumor types (lung cancer, breast cancer, pancreatic cancer, kidney cancer), complement proteins C1q, C1s, C3, C4, anaphylatoxins C3a and C5a and their receptors and regulatory proteins (such as factor B, factor H, factor I, CD55 and CD59) are most often overexpressed." (PMID 40596619, 2025). "Increased C3 levels are also detected in breast cancer patients." (PMID 34707103, 2021). "Upon analysis of the clinical data from human invasive breast cancer mRNA profiles for tumor samples of 526 invasive breast cancer patients, we found that C3 expression was positively correlated with CAFs markers a-c and its effector cytokines in human breast cancer tissues." (PMID 31931851, 2020).
breast cancer (continued). "The complement C3 cleavage fragments were found to be deposited in the premetastatic lungs as early as 4 days after injecting tumor cells into the mammary fat pad in a model of breast cancer (before any tumor cells are present in the lungs)." (PMID 30061895, 2018). "Moreover, sialylation changes of A1BG and Complement C3 were demonstrated in blood samples of control and breast cancer patients, suggesting that such modification in the protein glycosylation pattern of these proteins may also serve as a potential biomarker." (PMID 34885011, 2021). "Cancer cells have an increased capacity to activate the complement system, where some types of cancers such as breast cancer and papillary thyroid cancer were found to have deposits of C5b-9 MAC complex, C3 and C420,21." (PMID 41526546, 2026). "Similar studies have shown that complement 3 (C3) is increased in lung mesenchymal stromal cells, and C3-C3a receptor axis promotes neutrophil recruitment and NET formation, which facilitates breast cancer cell metastasis to the lungs." (PMID 36993957, 2023). "Lin and colleagues showed that ST3GAL1-mediated sialylation of CD55 renders better inhibition of the complement system at C3 level and that ST3GAL1 silencing results in increased C3 deposition and increased CDC-mediated killing of breast cancer cells." (PMID 35860237, 2022). "The most significant ones include TFF1, CCND1, IGFBP4, C3, ADORA1, GREB1, and MYC, which have been shown by candidate gene analysis to be estrogen regulated genes in breast cancer cell lines." (PMID 21878096, 2011). "Conversely, inflammatory proteins, such as complement C3, complement C9, complement factor B, and complement 4B, were significantly elevated in TNBC patients, suggesting a shift toward a pro-inflammatory HDL-C phenotype in aggressive breast cancer." (PMID 40430118, 2025). "This RhoA-independent effect was also confirmed by the absence of the effect of C3 exoenzyme on Cox-2 at transcript and protein levels on these breast cancer cells." (PMID 12771933, 2003). "We then used machine learning methods to perform feature selection and reduction, which generated a clinical-friendly scoring system consisting of 5 genes (C3, CD27, GFPT2, GMFG, and HLA-DPB1) that could be used to predict clinical outcomes in breast cancer patients." (PMID 37287069, 2023). "An earlier onset of spontaneous Her2+ mammary cancers and lung metastases, paralleled by reduced mouse survival, was observed in neuT females lacking C1qA (neuT-C1KO) or C3 (neuT-C3KO) complement components." (PMID 35203439, 2022).
Stroke (60 papers, 2010 to 2025). Sudden impairment of blood flow to a part of the brain due to occlusion or rupture of an artery to the brain. "The Lyz2-Cre macrophage model has elucidated the role of peripheral macrophage-derived C3 in shaping CNS immune responses and antigen presentation, particularly in border-associated macrophages (BAMs) that influence post-stroke inflammation." (PMID 41002405, 2025). "Its role in the acute and chronic post-stroke phase has been corroborated in preclinical stroke models, where inhibition or genetic deletion of C3 was associated with reduced infarct volumes and improved neurological outcomes." (PMID 41342963, 2025). "The plasma C3 level is associated with the prognosis of IS at 3 months post-stroke, and positively correlated with clinical outcome." (PMID 39012667, 2024). "have shown that the combination of low C3 and low C4, accompanied with antiphospholipid antibodies, was associated with stroke." (PMID 36238309, 2022). "We have previously shown that microglia play a role in phagocytosis and elimination of C3 opsonized neurons acutely after stroke, and of C3 opsonized synapses after TBI, which is associated with cognitive decline." (PMID 33879257, 2021). "In a cohort of 2,399 patients with SLE, 55% had low C3 levels and 47% had low C4 levels, and neuropsychiatric manifestations, including seizure, psychosis, and stroke, were significantly associated with both low C3 and C4 levels." (PMID 34548991, 2021). "Results on three clinical studies on stroke or recurrent pregnancy loss were in accord with our observations that high C4 and/or high C3 plasma protein levels are associated with thrombosis or recurrent pregnancy loss." (PMID 31134052, 2019). "Complement components that were significantly downregulated after stroke, C3b/ iC3b, C3, Factor H (fH) and Properdin, are more associated with the alternative pathway of complement activation." (PMID 31700615, 2019). "Additional investigations in vivo in a mouse model deficient for either C3aR or C3 revealed that C3a affects not only bleeding time but also tissue injury after stroke, myocardial infarction and thrombosis." (PMID 31402914, 2019). "Serum levels of C3, C3c, and C4 were also associated with increased stroke severity in cardio-embolic stroke patients." (PMID 26322048, 2015). "Additional differences between C3-deficient and complement-inhibited mice were the extent of microglial activation and post-stroke mortality." (PMID 26714866, 2015). "The follow-up phase plasma C3 levels in the upper third were found to be associated with an increased risk of unfavorable outcome at three months as well as two years after stroke in the CE group." (PMID 23977229, 2013). "We investigated association of plasma C3 and C3a levels to stroke, correlations to C-reactive protein (hsCRP), and associations with functional outcome at three months and two years post admission." (PMID 23977229, 2013). "In the SVD group, acute phase plasma C3 levels in the upper and middle third were associated with stroke in both models." (PMID 23977229, 2013). "In the CE group, high C3 levels at follow-up were associated with increased risk of unfavorable outcome at both three months and two years after stroke." (PMID 23977229, 2013). "Notably, analysis of 341 DE mRNA associated with stroke (259 upregulated, 82 downregulated) in the IR group revealed upregulation of genes like Ccl2, Cxcl1, C3, Serpine1, Adamts7, Csf3, Ptx3, MMP8, Lif, and Lcn2, and downregulation of Gdf10, Agtr2 and Shank3." (PMID 39170713, 2024). "Activation of complement components such as C3 and C5 has also been linked to platelet-mediated thrombosis with implications for disease development including, but not limited to, myocardial infarction, stroke, PE, and venous thromboembolism." (PMID 37759718, 2023). "The C3 complement protein-derived signaling peptide, C3a, has been implicated in contributing to both tissue damage and repair in conditions such as multiple sclerosis and stroke." (PMID 31272467, 2019).
Stroke (continued). "The follow-up phase plasma C3 levels in the upper third were associated with an increased risk of unfavorable outcome at three months (OR 7.12, CI 1.72–29.46, P = 0.007) as well as after two years (OR 8.25, CI 1.61–42.28, P = 0.011) after stroke." (PMID 23977229, 2013). "Follow-up plasma C3 levels in the upper third were associated with stroke in the SVD group only." (PMID 23977229, 2013). "Thus, the association between systemic C3 response and outcome after CE stroke could simply be explained by the extent of damage and impairment." (PMID 23977229, 2013). "Lastly, the CD11c-Cre dendritic cell model has highlighted the role of dendritic cell-derived C3 in CNS immune surveillance and T cell priming, with implications for post-stroke antigen presentation and chronic neuroinflammation." (PMID 41002405, 2025). "Multiple lines of evidence derived from diverse experimental models suggest that complement C3 is central to stroke pathology." (PMID 41002405, 2025). "Of note, IL1 signaling and C3 protein levels are known to be increased following stroke and correlate with worse clinical outcomes in ischemic stroke patients." (PMID 40362325, 2025). "One point that is noteworthy is that C3 is a target of Bothrops toxins, and in stroke, elevated plasma C3 levels are markers of worse prognosis in patients with ischemic stroke." (PMID 41000389, 2025). "The complement system becomes overactivated after stroke, with Complement Component 1q (C1q) and complement component 3 (C3) rapidly accumulating around neurons and tagging damaged synapses within 24 h." (PMID 41367136, 2025). "Collectively, these compartment-specific approaches offer high-resolution insight into how localized C3 expression contributes to stroke pathology." (PMID 41002405, 2025). "Specifically, PPARα KO led to increased expression levels of Gadd45b, Nppa, Hdc, Lcn2, Il6, Sox4, Marcksl1, Saa3, Ucn2, Met, Dusp10, Elovl7, Ngf, C3, Il11, Hmox1, Alox5, Tnfsf9, Angptl4, Plin2, H19, Csf2rb, Atf3, and Col7a1 following stroke." (PMID 40362325, 2025). "While historically considered a mediator of neuroinflammation and tissue damage, growing evidence suggests that complement components, particularly C3 and its receptor, C3aR, also participate in neuroprotection and post-stroke regeneration." (PMID 41002405, 2025). "In recent studies, C1q, C3, and C4 were found to be significantly increased and they are closely related to synaptic pruning after stroke." (PMID 39012667, 2024). "Following a stroke, the complement cascade is triggered, leading to the accumulation of C1q and C3 around neurons." (PMID 39012667, 2024). "Translationally, C3 and C3a levels have been shown to be upregulated in plasma from ischemic stroke patients, similar to complement deposits in human post-stroke brain tissue." (PMID 37273022, 2023). "C3 inhibition attenuates ischemic brain injury; however, conflicting studies show that C3 deficiency impaired neurogenesis and implied neuroprotective bioactivity of C3 in the sub-acute phase of stroke." (PMID 37270727, 2023). "In light of the ischemia-induced upregulation of C3 in sprouting neurons and the stimulatory effect of C3a on neurite outgrowth in vitro, these findings implicate C3a-C3aR as a contributing factor in post-stroke axonal plasticity." (PMID 34379293, 2021). "A total of 190 genes such as complement component 3 (C3) and C6 were expressed in the brain cells 14 days after stroke onset and peaked 14 days later." (PMID 34094642, 2021). "Nevertheless, hypoxic-ischemic injury in C1q knockout mice have reduced macrophage activation and C3 deposition in the ischemic brain compared with WT, suggesting that downstream complement activation is involved in stroke pathology." (PMID 33239010, 2020). "In patients suffering a stroke, plasma levels of C3a, C3, C4, C5, C5a, factor B, MBL, MASP-1/2, and MAC are all elevated and ficolin-1, ficolin-2, and ficolin-3 reduced." (PMID 31417544, 2019).